RNU6-809P (RNA, U6 small nuclear 809, pseudogene)
Gene: Small nuclear RNA gene on chromosome 1 (64,028,894 to 64,029,000, reverse strand). Ensembl gene ENSG00000207190.
Homologues: Orthologues: chimpanzee U6 (99% identical), macaque U6 (84% identical), mouse Gm26111 (79% identical). Paralogues in human: RNU6-1011P (90% identical), RNU6-38P (90% identical), RNU6-1005P (89% identical), RNU6-16P (89% identical), RNU6-639P (89% identical), RNU6-1 (88% identical), RNU6-1145P (88% identical), RNU6-12P (88% identical), RNU6-13P (88% identical), RNU6-144P (88% identical), RNU6-17P (88% identical), RNU6-18P (88% identical), and 1286 more.